F9 (coagulation factor IX)
Diseases named in the same sentence as F9 in open-access papers (continued):
Sharing a sentence is not in itself a finding about the gene and the disease.
hemophilia B (continued). "These vectors targeting the expression of a canine factor IX transgene in hepatocytes were well tolerated and provided a stable long-term production of coagulation factor IX in dogs with hemophilia B." (PMID 31771194, 2019). "In the case of hemophilia B, F9 is primarily expressed in liver and analysis of RNA transcripts from peripheral blood to assess splicing is not reliable (Green, Rowley, & Giannelli, 2003)." (PMID 31257730, 2019). "For example, coagulation factor IX (NP_989,674.1), a blood clotting factor responsible for hemophilia B in humans, had decreased transcriptional expression in the 10 and 20 mg/kg/d exposures when combined with dietary restriction." (PMID 30518325, 2018). "Gene therapy provides hope for a cure for patients with hemophilia B by introducing a functional gene copy of F9 to repair or compensate the defective gene." (PMID 30301136, 2018). "Recently, a long-acting recombinant coagulation factor IX–albumin fusion protein (rIX-FP) has been approved for the management of hemophilia B. Fusion to albumin potentially enables internalized proteins to engage FcRn and escape lysosomal degradation." (PMID 29523681, 2018). "A different study focusing on the coagulation factor IX-Fc (FIX-Fc) fusion protein described increased immunogenicity of the FIX-Fc in comparison with the native FIX in a hemophilia B mouse model." (PMID 28952523, 2017). "Long-term therapeutic levels of coagulation Factor IX have recently been achieved in hemophilia B patients treated with a single intravascular administration of the recombinant AAV2/8 vector." (PMID 22903887, 2012). "Similarly, etranacogene dezaparvovec represents a promising innovation for hemophilia B, offering a cost-effective alternative to lifelong coagulation factor IX therapy, though the evidence remains limited due to its recent approval." (PMID 40805927, 2025). "Notably, a clinically relevant pro-drug of parthenolide (DMAPT) also displayed a similar trend of enhancing AAV2-driven coagulation factor IX expression in hemophilia B mouse models." (PMID 41140178, 2025). "Importantly, stable expression of factor IX protein has been shown to persists even for over 11 years after a single administration of the scAAV8-co F9 vector in patients with hemophilia B." (PMID 40178764, 2025). "For example, continued injections of coagulation factor IX (FIX) in hemophilia B patients that have developed antibodies against FIX may result in anaphylaxis." (PMID 39066287, 2024). "Here, we describe a hemophilia B patient, who apparently profits from the presence of an Alu Sx element harboring three functional PAS, as they appear to substitute the function of the mutated authentic F9 PAS1." (PMID 39423215, 2024). "We created knock-in (KI) mice that expressed human F9 cDNA without or with the hemophilia B mutation (I316T)." (PMID 37076593, 2023). "Females who have a deficient F9 gene on one X chromosome (traditionally termed hemophilia B carriers) are likely to have <60% of normal FIX levels, and ~25% of carriers have factor levels < 40%, similar to patients with mild hemophilia B." (PMID 35207344, 2022). "Here, we targeted the human coagulation factor IX (hFIX) cDNA into a hemophilia B mouse model." (PMID 35359664, 2022). "Hemophilia B is a rare inherited genetic bleeding disorder caused by a deficiency or lack of coagulation factor IX, the gene for which (F9) is located on the X chromosome." (PMID 35883203, 2022). "Hemophilia B is a recessive congenital X-linked bleeding disorder caused by mutation in the F9 gene, which results in a deficiency or absence of coagulation factor IX (FIX)." (PMID 35207344, 2022). "However, until now, only one albumin-fusion therapeutic protein is available on the market: Idelvion® (coagulation factor IX to treat hemophilia B)." (PMID 34490225, 2021).
hemophilia B (continued). "Another globally shared region contains the F9 gene, which encodes the coagulation factor protein FIX and is involved in Hemophilia B. In this case, the F9 region harbours windows under positive selection in the 99.9th percentile reported by iHH12, and reflects a region that spans up to ∼50 kb." (PMID 34646300, 2021). "Hemophilia B (HB; OMIM 306900) is a rare X‐linked recessive hemorrhagic disorder caused by a deficiency or abnormality in coagulation factor IX (FIX) due to mutations in the F9 gene, affecting 1 in 30,000 male live births (Bolton‐Maggs & Pasi, 2003)." (PMID 32875744, 2020). "INS regulates vascularization; APOH, F2, and ICAM regulate platelet activation and adhesion; AGT regulates blood vessel contraction; TNF and CCL2 regulate blood chemokine in circulation; F9 regulates onset Hemophilia B, and PON1 inhibits onset cardiovascular disease." (PMID 32753925, 2020). "Hemophilia B is an inherited X chromosome–linked disorder characterized by impaired blood clotting owing to the absence of functional coagulation factor IX." (PMID 26840952, 2016). "Previous reports have shown that ZFNs and even a nuclease‐free approach are also efficient and since they insert F9 cDNA under the control of the albumin or F9 promoters, they have potential application in any case of hemophilia B regardless of the mutation." (PMID 27138565, 2016). "In this respect, rAAV were used for hepatic delivery in adult and newborn mice of ZFNs to intron 1 of the factor 9 gene (F9) and as DNA donor an acceptor splicing sequence and the cDNA of exons 2–8 to obtain production of factor IX in a humanized murine model of hemophilia B." (PMID 27138565, 2016). "Hemophilia B (Christmas disease) (HB) is a very rare disease; it is an X-linked, recessive bleeding disorder characterized by the deficiency or absence of the coagulation factor IX (FIX)." (PMID 35782080, 2022). "Our patient was diagnosed with mild hemophilia B after finding an 11 Mb deletion of Xq26.3q28 that included the following genes among others IDS,SOX3,FMR1,AFF2, and F9." (PMID 30264515, 2018). "Since the size of the F9 gene is small and a slight increase of FIX levels will modify the bleeding diathesis, hemophilia B is relatively ideal for gene therapy." (PMID 30301136, 2018). "Gene therapy for Hemophilia B uses an AAV5 vector to deliver a functional copy of the F9 gene into liver cells, allowing patients to achieve sustained production of functional factor IX and thereby reducing the frequency of bleeding episodes and the need for regular factor IX infusions." (PMID 39985020, 2025). "Clinicaltrials.gov lists 23 clinical trials of hemophilia B gene therapies (active and interrupted), of which most candidate drugs are AAV-based therapies, with the exception of a study involving lentiviral delivery of the F9 gene to autologous hematopoietic and mesenchymal stem cells (NCT03961243)." (PMID 37445943, 2023). "We believe that gene therapy of monogenic diseases like hemophilia B would most likely not benefit from integrating viral hybrid vectors, because non-integrating HDAdV and AAV vectors were already shown to result in long-term expression of the human coagulation factor IX in mice and dogs." (PMID 21994594, 2009). "However, approximately 5% of adult patients with hemophilia B develop inhibitory antibodies against recombinant forms of FIX, highlighting the need for the development of universal gene therapy strategies using CRISPR-Cas editing of F9, employing non-viral delivery systems." (PMID 40725041, 2025).
hemophilia (110 papers, 2006 to 2026). Hemophilia is a genetic disorder characterized by spontaneous hemorrhage or prolonged bleeding due to factor VIII or IX deficiency. "Hemophilia is an X-linked recessive inherited hemorrhagic disease primarily caused by reduced activity or deficiency of coagulation factor VIII (FVIII) or coagulation factor IX (FIX)." (PMID 41087175, 2025). "In the hemophilia family, the proband (child) carries a hemizygous mutation of F9 gene c.424G>T on ChrX, which was inherited from the mother." (PMID 36810160, 2023). "Hemophilia is an inherited bleeding disorder due to mutations in F8 or F9 genes encoding for factor VIII (FVIII) or factor IX (FIX) protein, respectively, which are necessary factors for proper blood coagulation and hemostasis." (PMID 35508619, 2022). "Hemophilia mice that express a mutant allele of human coagulation factor IX (FIX) containing nonsense mutation R338X were treated with eRF1- or eRF3a-ASO." (PMID 31070517, 2019). "The authors then elegantly demonstrate that this mutation is indeed responsible for hemophilia by generating a mouse strain containing the mutation and presenting with normal levels of F9 but with the hemostasis defect." (PMID 27138565, 2016). "Multiple mutations within this region are associated with defective expression of F9 and clinical hemophilia." (PMID 25279814, 2014). "In addition, the mutant has the characteristics of mouse embryonic stem cells, and this point mutation affects F9 gene transcription and translation, which can be used as a disease model for studying the pathogenesis and treatment of hemophilia at the stem cell level." (PMID 35883203, 2022). "In patient 43, a microdeletion of Xq27.1 affecting the F9 gene was reported as a secondary finding, and the diagnosis of hemophilia was clinically confirmed." (PMID 37940764, 2024). "The European Association for Haemophilia and Allied Disorders (EAHAD) Coagulation Factor IX Gene (F9) Variant Database (accessed September 20, 2021) currently lists 1244 variants in F9 including insertions and deletions." (PMID 34680886, 2021). "Although the roles of F9 have been extensively explored in hemophilia, there are very few studies that have investigated its roles in cancer progression." (PMID 30807603, 2019). "While minimally impacting the normal transcriptome, Upf3b-ASO treatment significantly stabilizes the PTC-containing dystrophin mRNA in mdx mice and coagulation factor IX mRNA in a hemophilia mouse model." (PMID 29334995, 2018). "IDLV-mediated and hepatocyte-targeted coagulation factor IX (FIX) expression prevented the induction of neutralizing antibodies to FIX even after antigen rechallenge in hemophilia B mice and accounted for relatively prolonged therapeutic FIX expression levels." (PMID 21520180, 2011). "Hemophilia is an X‐chromosome‐linked recessive inherited disorder of coagulation dysfunction that is classified according to the type of defective coagulation factor as type A (coagulation factor VIII deficiency) and type B (coagulation factor IX deficiency)." (PMID 40264735, 2025). "Hemophilia (HB) is an X-linked, recessive bleeding disorder characterized by the deficiency or absence of the coagulation factor IX." (PMID 35782080, 2022). "There are two main types of hemophilia: hemophilia A, which is caused by a deficiency of coagulation factor VIII (FVIII) and accounts for 80–85% of the total hemophilia population, and hemophilia B, which is caused by a deficiency of coagulation factor IX." (PMID 35252176, 2022). "In hemophilia B mice with a F9 gene deletion, we reconstituted some of these findings: the CD8+ T cell responses against hF.IX was more robust and also more functional using the scAAV vector, with infiltrating T cells rapidly eliminating hF.IX expressing muscle fibers." (PMID 24460861, 2014).
hemophilia (continued). "Most of the mutations in haemophilias leads to insufficient activity of the tenase complex, brought about either by a deficiency of coagulation factor VIII cofactor activity (haemophilia A) or coagulation factor IX enzyme activity (haemophilia B)." (PMID 22423892, 2012). "It is demonstrated that transfecting hemophilia B mice with AAV8 vectors carrying S. aureus Cas9 (SaCas9) and gRNA can successfully restore coagulation factor IX secretion of hepatocytes." (PMID 34446084, 2021).
hemophilia A (92 papers, 2005 to 2026). The most common form of hemophilia characterized by spontaneous or prolonged hemorrhages due to factor VIII deficiency. "Currently, there are two FDA approved bispecific antibodies for clinical use: blinatumomab, used to treat acute hematological malignancies via CD3 and CD19, and emicizumab, which binds the coagulation factor IX and factor X for treatment of hemophilia A." (PMID 34504657, 2021). "Haemophilia A and B (HA and HB, respectively) are severe bleeding disorders caused by mutations in the genes encoding coagulation factor VIII (FVIII) or coagulation factor IX (FIX), respectively." (PMID 28384182, 2017). "Hemophilia A and B are X-linked recessive disorders resulting from more than 3,000 known DNA variants in the genes encoding coagulation factor VIII (F8) and factor IX (F9), respectively." (PMID 32497118, 2020). "The quality of some of the human plasma derived drugs such as coagulation factor VIII and coagulation factor IX which can be used for the treatment of hemophilia A and B, depends on their activity which may be affected by filtration." (PMID 22615604, 2010). "Haemophilia A and Haemophilia B are X-linked inherited bleeding disorder caused by a decreased activity or lack of coagulation factor VIII cofactor activity (haemophilia A) or coagulation factor IX enzyme activity (haemophilia B) due to heterogenous mutations in the F8 and F9 coding gene." (PMID 22423892, 2012).
thrombophilia (9 papers, 2020 to 2025). A condition characterized by an abnormally high level of thrombi. "Several Reactome pathways enriched among genes involving variants classified as P/LP in this study were related to hemoglobin and coagulation including “defective factor IX causes thrombophilia” (REAC:R-HSA-9672383; F8, F9; adj." (PMID 37745687, 2023). "They reported that OC users have greater coagulation factor IX plasma levels and lower plasma PS values, both of which can potentially tip the coagulation cascade towards hypercoagulability." (PMID 32992471, 2020).
breast carcinoma (6 papers, 2003 to 2025). "The authors found that coagulation factor IX (F9) loss prevents cell cycle arrest and senescence in breast cancer cells treated with palbociclib." (PMID 40650785, 2025). "When analysing other transcripts implicated in the intrinsic coagulation pathway where F9 is involved, most are also upregulated in breast cancer, while transcripts within the extrinsic pathway are mainly downregulated." (PMID 35184131, 2022). "Interestingly, low expression levels of F9 in different subtypes of breast cancer (basal, luminal A and luminal B) are also associated with poor prognosis and lower disease-free survival probability." (PMID 35184131, 2022). "Using a human genome-wide CRISPR/Cas9 library it has been identified that loss-of-function of the coagulation factor IX (F9) gene prevents the cell cycle arrest and senescent-like phenotype induced by Palbociclib in MCF7 breast cancer." (PMID 36497228, 2022). "Altogether, these data show the potential of using F9 levels as a biomarker for patient stratification not only to predict response to CDK4/6 inhibitors but also as a prognostic marker to determine overall survival in breast cancer." (PMID 35184131, 2022). "Importantly, high levels of F9 expression are a sign of good prognostic for survival in breast cancer." (PMID 35184131, 2022). "TGFβR binding (F9) regulates insulin-like growth factor binding protein (F5) (IGFBP)-3 production, which is a major antiproliferative factor and a key element for TGFβ-induced growth inhibition in breast cancer cells." (PMID 24997799, 2014).
COVID-19 (5 papers, 2021 to 2025). A disease caused by infection with severe acute respiratory syndrome coronavirus 2. "In the protein combination, 4 proteins including F11, F9, FGA and FGG are involved in the blood coagulation cascade, and all of them were higher expressed in COVID-19-children than those in healthy children or COVID-19-adults." (PMID 34335977, 2021).
thrombosis (5 papers, 2016 to 2024). "It has been also reported that high levels of coagulation factor IX are associated with an increased risk of venous thrombosis." (PMID 35685509, 2022).
hepatocellular carcinoma (4 papers, 2011 to 2025). A malignant tumor that arises from hepatocytes. "Interestingly, treatment with TA attenuated MSG-induced upregulation of Aurora kinase A (Aurka) and Cyclin B2 (Ccnb2), and downregulation of Coagulation Factor IX (F9) and Cytochrome P450 2E1 (Cyp2e1) gene expressions, in which these genes are hepatocellular carcinoma-associated key genes." (PMID 39925850, 2025). "Of all the cancer cell lines analysed, the renal adenocarcinoma cell line (ACHN) was the only cell line to upregulate F9 with Palbo and Abema, while the human colorectal adenocarcinoma cell line (HT29) and the hepatocellular carcinoma cell (SNU-387) increased F9 mRNA expression only with Palbo." (PMID 35184131, 2022).
epilepsy (3 papers, 2020 to 2025). A brain disorder characterized by episodes of abnormally increased neuronal discharge resulting in transient episodes of sensory or motor neurological dysfunction, or psychic dysfunction. "Measurement of proteins in serum exosomes from patients with epilepsy revealed that coagulation factor IX (F9) and thrombospondin-1 represent potential new markers for the diagnosis of epilepsy." (PMID 34588957, 2021). "Based on the statistical results, we expanded the sample size (200 pairs of epilepsy patients and healthy controls) to further verify the differential expression of F9 and TSP-1 in serum exosomes by ELISA." (PMID 32848539, 2020). "The results showed that the expression of F9 in serum exosomes of epilepsy patients was higher than that in serum exosomes of healthy controls." (PMID 32848539, 2020). "To further validate and explore the relationship between exosomes and epilepsy, we further validated F9 and TSP-1 in human brain tissue exosomes." (PMID 32848539, 2020). "In the KA-induced epilepsy model, F9 expression was higher in both the cortex and hippocampus of epileptic mice." (PMID 32848539, 2020). "Comparing the epilepsy patients with the healthy controls, the capacity of F9 and TSP-1 expression to predict epilepsy yielded an area under the curve (AUC) of 0.7776 (95% CI, 0.7306–0.8246) and 0.8534 (95% CI, 0.8152–0.8916), respectively." (PMID 32848539, 2020). "One study highlighted specific exosomal proteins, such as F9 and TSP-1, present in the serum of individuals with epilepsy, suggesting their potential as biomarkers for the detection of epilepsy." (PMID 40533746, 2025). "Based on the statistical results, we verified the expression of F9 and TSP-1 in the serum exosomes of 200 pairs of epilepsy patients and healthy controls." (PMID 32848539, 2020). "Our research data indicate that F9 and TSP-1 are reliable biomarkers for the diagnosis of epilepsy." (PMID 32848539, 2020). "We have discussed the exosomal proteins F9 and TSP-1 as biomarkers for the diagnosis of epilepsy." (PMID 32848539, 2020). "Bioinformatics GO analysis showed that F9 and TSP-1 may be involved in many physiological processes of epilepsy." (PMID 32848539, 2020).
desmoid fibromatosis (2 papers, 2003 to 2022). "Despite a series of RTK upregulation, the F9 FAP-associated desmoid fibromatosis that received only gross total resection, did not recur three years post resection, emphasizing the importance of the surgical treatment for this neoplasm." (PMID 35978432, 2022).
factor XI deficiency (2 papers, 2024 to 2025). A coagulation disorder characterized by the partial or complete absence of factor XI activity in the blood. "If half of the heterozygotes of this variant could trigger the lack of coagulation factor IX, the morbidity of Factor XI deficiency in the Chinese population would be far higher than the currently speculated (0.1–246.2 × 10−6)." (PMID 39606185, 2024).
breast tumour (1 paper, 2022). "We find that downregulation of the coagulation factor IX (F9) using sgRNA and shRNA prevents the cell cycle arrest and senescent-like phenotype induced in MCF7 breast tumour cells upon Palbociclib treatment." (PMID 35184131, 2022).